CATSPER4 (cation channel sperm associated 4)
Description:
Pore-forming subunit of the CatSper complex, a sperm-specific voltage-gated calcium channel that plays a central role in calcium-dependent physiological responses essential for successful fertilization, such as sperm hyperactivation, acrosome reaction and chemotaxis towards the oocyte.
Tractability: Small molecule: it belongs to a druggable protein family. Antibody: its Gene Ontology location is reachable by antibodies, with high confidence; UniProt predicts a signal peptide or a membrane-spanning region. PROTAC: ubiquitination databases record sites on it.
Gene: Protein-coding gene on chromosome 1 (26,190,561 to 26,202,968, forward strand). Ensembl gene ENSG00000188782.
Subcellular location: Cell projection, cilium, flagellum membrane
Pathways (Reactome):
Reproduction: Sperm Motility And Taxes
Gene Ontology:
Molecular function: protein binding; voltage-gated calcium channel activity; calcium-activated cation channel activity; monoatomic ion channel activity
Biological process: flagellated sperm motility; sodium ion transport; sperm capacitation; spermatogenesis; calcium ion transmembrane transport; monoatomic cation transmembrane transport; monoatomic ion transmembrane transport; monoatomic ion transport; transmembrane transport
Cellular component: acrosomal vesicle; CatSper complex; plasma membrane; sperm principal piece; membrane
Genetic constraint (gnomAD): Loss-of-function variants: 44 observed, 54.75 expected, observed/expected ratio (o/e) 0.8, 90% interval 0.63 to 1.03. The upper end of that interval is the gene's LOEUF score, 1.03, which puts it in group 4 of 6, group 1 being the genes least tolerant of losing a copy. Missense variants: 574 observed, 641.32 expected, observed/expected ratio (o/e) 0.9, 90% interval 0.83 to 0.96. Synonymous variants: 230 observed, 243.61 expected, observed/expected ratio (o/e) 0.94, 90% interval 0.85 to 1.05.
Homologues: Orthologues: chimpanzee CATSPER4 (97% identical), macaque CATSPER4 (93% identical), pig CATSPER4 (74% identical), rabbit CATSPER4 (74% identical), dog CATSPER4 (70% identical), rat Catsper4 (69% identical), mouse Catsper4 (66% identical). Paralogues in human: SCN8A (27% identical), CACNA1C (27% identical), SCN4A (27% identical), SCN5A (27% identical), SCN10A (26% identical), SCN1A (26% identical), SCN2A (26% identical), CACNA1D (26% identical), SCN3A (26% identical), SCN9A (25% identical), CACNA1S (25% identical), SCN11A (25% identical), and 14 more.
Diseases named in the same sentence as CATSPER4 in open-access papers:
CATSPER4 is named in the same sentence as 4 diseases in open-access papers, as found by Europe PMC text mining. Sharing a sentence is not in itself a finding about the gene and the disease. The quoted sentences say what the papers report.
asthenozoospermia (2 papers, 2017 to 2026). "In our study we detected a decrease of CatSper4 gene expression in asthenozoospermia and teratozoospermia group and an increase in the oligozoospermia and oligoasthenoteratozoospermia groups." (PMID 29492471, 2017).
infertile (2 papers, 2017 to 2023). "Jin and colleagues have stated that CatSper3-/- and CatSper4-/-male rats were infertile even they were showing normal mating attitude." (PMID 29492471, 2017). "In their study, they have shown that CatSper3-/- and CatSper4-/-rats were infertile despite their normal sperm count and motility." (PMID 29492471, 2017). "Knockout of CATSPER3 and CATSPER4 in male mice leads to complete infertility due to rapid loss of motility and absence of hyperactivated motility under capacitating conditions." (PMID 37799407, 2023).
CATSPER4 also shares sentences with these, for which no sentence is quoted: oligoasthenoteratozoospermia (1 paper); teratozoospermia (1).